ALB (albumin)
Diseases named in the same sentence as ALB in open-access papers (continued):
Sharing a sentence is not in itself a finding about the gene and the disease.
malnutrition (continued). "One of the biochemical exponents of increasing malnutrition may be reduced values of the albumin concentration." (PMID 36615736, 2022). "In contrast, malnutrition status may reduce plasma albumin levels, while systemic inflammatory responses have the same effect." (PMID 36407534, 2022). "Serum albumin level <3.5 g/dL in a stable and well-hydrated patient suggests malnutrition." (PMID 36589182, 2022). "Albumin, a biomarker of systemic inflammation and malnutrition, predicts survival in many cancers." (PMID 34660664, 2021). "To conclude, in this cohort of HF patients who initiated chronic HD, one-year mortality was higher in older patients and in patients with lower serum albumin levels and lower serum creatinine levels, highlighting the prognostic importance of malnutrition in these patients." (PMID 34640538, 2021). "Although it is controversial whether serum albumin levels directly indicate malnutrition, studies show that declining serum albumin levels serve as a marker of inflammation associated with nutritional risk and the risk of developing adverse clinical outcomes." (PMID 34616765, 2021). "Since BCAAs promote albumin synthesis, BCAAs could be beneficial in patients with HF and malnutrition, sarcopenia, or cachexia." (PMID 34912870, 2021). "Assessments using a single indicator of malnutrition, such as serum albumin or total cholesterol level, may be affected by various factors and not provide adequate information." (PMID 34034769, 2021). "Albumin has a long half-life as a body protein, so hypoalbuminemia reflects prolonged malnutrition." (PMID 34548054, 2021). "Besides physical functionality, malnutrition was mainly assessed as an indicator of frailty considering pre-interventional levels of serum albumin." (PMID 34640525, 2021). "Furthermore, low albumin concentration also means malnutrition, and this can negatively affect tumor immunity in the microenvironment." (PMID 33658561, 2021). "On the other hand, some studies assessed malnutrition through nutritional indices, which are calculated based on combinations of nutritional biomarkers (e.g., serum albumin and cholesterol), markers of inflammation (e.g., lymphocyte count), age, comorbidities, etc.." (PMID 33803339, 2021). "Our findings suggest that the mGPS, which is a combination of serum CRP and albumin levels, might serve as an indicator of chronic inflammation and malnutrition, which result in a worse prognosis." (PMID 33866376, 2021). "The decrease in albumin may be a powerful prognostic marker, mainly as a result of malnutrition and inflammation." (PMID 34640538, 2021). "Malnutrition and weight loss were significantly associated with pulmonary hypertension, heart failure, albumin levels, and the extent of skin fibrosis, but not advanced age." (PMID 34829464, 2021). "Malnutrition has been estimated depending on various parameters that may include BMI, serum albumin, and skeletal muscle mass." (PMID 35011831, 2021). "Albumin is one of the biochemical indices that decrease during malnutrition." (PMID 33673581, 2021). "We found similar mean albumin levels and correlation with nutrition status as these studies, indicating that it might be used as an indicator for malnutrition in gynecological cancer patients when full nutritional assessment is not possible." (PMID 35127741, 2021). "Albumin is considered as a nutritional status indicator; therefore, hypoalbuminemia might serve as a marker for malnutrition." (PMID 34357140, 2021). "The underlying mechanisms of PNI in chordoma remain unclear and we hypothesize that low PNI patients harbor low levels of albumin and potential malnutrition, which may mediate host immune-suppression in coordination with lymphocytopenia." (PMID 33718126, 2021). "Albumin is produced by the liver and is an indicator of malnutrition." (PMID 33859292, 2021). "Thus, analysis of serum albumin levels as an expression of malnutrition was used to investigate the shrinking component." (PMID 34640525, 2021).
malnutrition (continued). "Based on the albumin levels upon the patients’ admission, normal nutritional status was identified in five subjects (10.0%), mild malnutrition was found in nine subjects (18.0%), while 19 subjects (38.0%) and 18 subjects (36.0%) presented moderate and severe malnutrition, respectively." (PMID 33669609, 2021). "Serum albumin level alone may sufficiently reflect malnutrition in hospitalized COVID-19 patients, especially in highly vulnerable individuals." (PMID 33803339, 2021). "In patients with EC, malnutrition, relevant to decreased serum albumin and AGR levels, could be another mechanism of poor survival." (PMID 34128338, 2021). "Another important role of albumin is that of a clinical biomarker of malnutrition." (PMID 33450916, 2021). "The LBP group had lower abdominal trunk and knee extensor muscle strength, lower serum albumin, and hemoglobin levels as blood biomarkers associated with malnutrition risk, and higher LS test scores than the non-LBP group." (PMID 33493191, 2021). "Although plasma albumin concentration is widely used as a marker of protein intake and malnutrition, the association is not unequivocal, and it is not reliable by itself; e.g., dehydration can increase plasma albumin concentration." (PMID 34444923, 2021). "Additionally, these studies recruited patients with mild to severe malnutrition defined by BMI, arm circumference, serum albumin, dietary intake, and subjective global assessment scores, thus highlighting recruitment without PEW diagnostic criteria." (PMID 34977109, 2021). "In turn, zinc in circulation is predominantly bound to albumin; in conditions of severe malnutrition, inflammation and CLD, there may be a reduction in its circulating level." (PMID 34076201, 2021). "CGA (ADL, IADL, MMSE, GDS, Vitality Index) was performed, along with assessment of body compositions (appendicular muscle mass, abdominal muscle mass, body fat mass) and blood malnutrition biomarkers (serum albumin, pre-albumin, 25-hydroxy vitamin D, zinc, hemoglobin concentrations)." (PMID 33529213, 2021). "Nevertheless, CRP may indicate whether serum protein concentrations of albumin are reduced because of inflammatory processes or malnutrition." (PMID 34072686, 2021). "In another cross-sectional study that examined serum albumin levels as an index of nutritional state in diabetic patients on HD, malnutrition prevalence was not linked to sex." (PMID 34225818, 2021). "Also, other nutritional indices suggest the presence of malnutrition such as reduced values of albumin, white and red blood cells, and haemoglobin." (PMID 34809654, 2021). "Medically, serum ALB may be used for evaluating the nutritional condition in cancer patients, as malnutrition can be a function of prognostic significance in cancer cases." (PMID 34603055, 2021). "Patients suffering from malnutrition had a significantly longer duration of hospitalization, higher hospitalization expenses, and significantly lower body weight and serum albumin when discharged from the hospital than patients the ones who were not malnourished." (PMID 34496796, 2021). "Nutrition treatment becomes extremely challenging since additional determinants of malnutrition may be present, including reduced food intake and/or defective absorption of nutrients and impaired albumin synthesis." (PMID 34444908, 2021). "Low albumin is often used as a biochemical marker of malnutrition and poor nutritional status, which may result in protein synthesis degradation and muscle weakness." (PMID 33949807, 2021). "Low levels of serum albumin can occur in patients with malnutrition and chronic infection." (PMID 34069272, 2021). "However, prior research has mostly focused on the geriatric populations, elective orthopaedic surgeries, and albumin and prealbumin as serum markers for malnutrition." (PMID 34768533, 2021).
malnutrition (continued). "While the body mass index (BMI) and albumin (ALB) can be used as primary screening indicators for malnutrition in HAE patients, the NRS 2002 method may be more reliable and prudent in assessing nutrition in HAE patients." (PMID 32092109, 2020). "They assessed malnutrition with BMI, serum albumin and total cholesterol levels." (PMID 33346224, 2020). "The Malnutrition Screening Tool (MST), Controlling Nutritional Status (CONUT), Geriatric Nutritional Risk Index (GNRI), Malnutrition Universal Screening Tool (MUST), body mass index (BMI), serum albumin, prealbumin, total protein, vitamin D and lymphocyte count are also used." (PMID 33291800, 2020). "It is known that albumin is not simply a marker of malnutrition but also reflects underlying inflammation and comorbidities, particularly cardiac comorbidities, with lower levels of albumin being related to inflammation and mortality." (PMID 32932809, 2020). "One study reported that comorbidities can be the reason for poor prognosis in patients with ESKD or serve as a marker for poor prognosis in patients receiving dialysis and that a low serum albumin concentration may indicate malnutrition." (PMID 32295526, 2020). "Likewise, advanced CKD (eGFR < 30) increases the likelihood of malnutrition (albumin < 3,5 g/dL) more than three times (five times after adjusting for comorbidities and country)." (PMID 33008315, 2020). "A lower score of mSIS indicates an elevated NLR and/or low level of albumin, which might indicate immunological response, malnutrition, and cachexia." (PMID 33101044, 2020). "Any decline in the levels of serum proteins (TP, albumin, and globulin) may be the result of hepatic insufficiency, malnutrition, and active inflammation, which may be due to the recurrent infections and immune deficiency." (PMID 32708616, 2020). "We have recently reported the association of low serum albumin with the degree of inflammation rather than malnutrition in patients with pulmonary sarcoidosis." (PMID 31936687, 2020). "Indeed, malnutrition (defined as a serum albumin level of < 2.5 g/dL) was identified as a predictor of aspiration pneumonia after RT alone." (PMID 32131771, 2020). "We hypothesis that this may be due to impaired protein synthesis due to patient malnutrition as noted by serum albumin and chronic inflammation, which is common among dialysis patients, in addition to poor sampling handling, especially during postage." (PMID 31931840, 2020). "Additionally, TBS positively correlated with lumbar L1-L4 T-score (p = 0.04), total femur T-score (p = 0.01) and with malnutrition/malabsorption markers, such as serum albumin levels (p = 0.02)." (PMID 32492873, 2020). "We aimed to emphasize the role of albumin as useful marker of the in-hospital malnutrition and frailty, to be integrated in the routinely assessment of patients for reconsidering ad hoc healthcare pathways after discharge from hospital, especially when dealing with fragile populations." (PMID 33261019, 2020). "TLC was less intensively studied comparing to serum albumin as a biomarker for malnutrition." (PMID 32660593, 2020). "The rest of the nutritional biomarkers currently have a controversial utility, although some review had identified albumin, prealbumin, hemoglobin, total cholesterol, and total protein, as useful biomarkers for adult malnutrition assessment of a surgical patient." (PMID 34221498, 2020). "Given that the permissible threshold for tolerance of albumin losses with highly permeable membrane remains unclear, long-term use of MCO or HCO membranes with HDF techniques may pose malnutrition risk." (PMID 33076282, 2020). "The inflammation results in a reduction in albumin production in the liver and fosters poor appetite, a non-iatrogenic factor implicated in malnutrition." (PMID 33076282, 2020). "Serum albumin may be a useful prognostic factor for survival and commonly utilised as an indicator for malnutrition." (PMID 32245389, 2020).
malnutrition (continued). "In contrast, in adult patients undergoing joint arthroplasty or hip fracture surgery, malnutrition defined by serologic markers (e.g. albumin, lymphocyte count, transferrin) was predictive for a higher risk of postoperative outcomes, such as wound complications." (PMID 32586289, 2020). "Serum albumin as a biomarker of protein status and malnutrition had been intensively investigated." (PMID 32660593, 2020). "Malnutrition, such as a decrease in albumin levels, is generally reported in patients after OHS." (PMID 33364510, 2020). "The nutritional assessment results varied depending on the BIA, SGA and serum albumin parameters and it is suggested that development of more specific tools that can identify malnutrition among CKD patient at the early stage of disease might be needed." (PMID 32711448, 2020). "As lower serum albumin level is an important indicator for malnutrition, inflammation, and overhydration, both overall and technique survival disadvantages in the non-NS PD group may be due to these poor clinical conditions." (PMID 32686569, 2020). "Among these, serum albumin level is the most important and commonly used biochemical index to reflect visceral protein storage, which is not only an indicator of malnutrition in dialysis patients but also a sensitive indicator to judge the mortality rate of patients on dialysis." (PMID 32490516, 2020). "One of the possible explanations is the prevalence of malnutrition in dialysis patients, as evidenced by reduced blood Hb and albumin which may lead to dysfunction of the immune system and hence, an increase risk of nosocomial infections." (PMID 32569265, 2020). "The MNA-SF and NRS-2002 tools showed that malnutrition risk was not significantly correlated with age, gender, serum albumin, but was correlated with lower phase angle, CRP, and muscle strength in elderly patients." (PMID 31388102, 2020). "As diet plays an important role in nutrition status, multimodel nutritional management, especially perioperative oral nutritional supplementation, would improve the level of serum albumin, and albumin infusion remains essential and beneficial for patients with malnutrition or undernutrition." (PMID 33170383, 2020). "Our study showed a significant difference in age, Handgrip strength, Albumin, and Hemoglobin between the frail diabetic patients and their counterparts, suggesting that reverse metabolism due to malnutrition in the elderly diabetic patients might be involved." (PMID 33076841, 2020). "However, the prognostic value of CRP and albumin in patients with reduced liver synthesis (e.g., malnutrition, liver cirrhosis, cancer, advanced age, or chronic heart failure) is limited." (PMID 32344777, 2020). "In addition, a low serum albumin level is a prognostic factor in cardiovascular disease, malnutrition, inflammatory reactions and nephrotic syndrome in elders." (PMID 31945744, 2020). "In this study, malnutrition was evaluated by the serum level of albumin." (PMID 33137946, 2020). "Serum albumin and prealbumin are two of the most commonly used indicators for assessing malnutrition, and malnutrition adversely affects the outcomes of cancer patients, in that it increases the incidence of infections, the length of hospital stay, and the risk of death." (PMID 31931816, 2020). "When comparing both procedures in terms of nutritional deficiency (Hb, albumin, vitamin B12, and INR), no statistically significant changes were found and none of the two procedures were found to impair these parameters more than the other." (PMID 32845477, 2020). "Serum albumin level and malnutrition according to SGA were significantly lower in A than in B." (PMID 31601040, 2019). "Hypoalbuminemia could be a consequence of an inflammation-mediated inability of HD patients to decrease the albumin fractional catabolic rate during protein restriction although it was presumed to arise primarily from malnutrition." (PMID 31048884, 2019).
malnutrition (continued). "The role of inflammation as a risk factor for malnutrition has been recognized and it was reported that elevated CRP levels could inhibit albumin synthesis in HD patients." (PMID 31048884, 2019). "It has been proven that both inflammation and malnutrition can suppress albumin synthesis." (PMID 31781312, 2019). "Biomarkers for malnutrition and inflammation are low serum albumin and elevated hs-CRP." (PMID 31480661, 2019). "As cancer progresses, serum albumin levels decrease due to inflammation and malnutrition." (PMID 31057617, 2019). "Hb and albumin levels secondary to malnutrition in malignant patients are expected to be low." (PMID 31933628, 2019). "Prealbumin (PA) is more sensitive to malnutrition than albumin." (PMID 30762804, 2019). "A probable explanation of this effect may be suppression in albumin synthesis by malnutrition and inflammation in an advanced stage of lung cancer." (PMID 30941358, 2019). "The rate of albumin synthesis is reduced in cases of malnutrition, malabsorption, or maldigestion, what could result from Thr deficient diets." (PMID 30834113, 2019). "As compared with the highest quartile group, more subjects in the lowest quartile group were of an older age; had lower hemoglobin and creatinine levels; had a higher prevalence of DM and malnutrition (serum albumin level < 3.6 g/dL); and higher serum transferrin saturation and ferritin levels." (PMID 31382911, 2019). "In addition, high EMAT/LVST was associated with low albumin, low ABI, and high bPEP/bET, which indicated malnutrition, PAD, and LV dysfunction, respectively." (PMID 31781303, 2019). "The groups differed significantly in the percentages of patients at risk of malnutrition, i.e. with MNA-SF score&lt;8, but BMI, WHR, mean albumin and hemoglobin levels were similar in OH+ and OH− groups, whereas BMI &gt;30 kg/m2 was observed significantly less frequently in OH+ group." (PMID 31233071, 2019). "Additionally, recent studies reported that prealbumin (PALB), serving as another important biomarker for nutritional status, is more sensitive to malnutrition than ALB." (PMID 31379941, 2019). "In addition, regardless of the used criterion for the detection and classification of malnutrition, albumin and prealbumin values were significantly lower and CRP higher than in normally nourished patients, consequently altering the Glasgow prognostic score." (PMID 31480635, 2019). "Serum albumin has been shown to be a limited predictor of malnutrition in this population." (PMID 31316299, 2019). "In our study, we found that fetuin-A levels were individually associated with the components of MIAC syndrome: calcification through VCS, atherosclerosis through CIMT, inflammation through hs-CRP, and malnutrition indirectly through BMI and albumin levels, in CKD patients as well as ESRD patients." (PMID 30761853, 2019). "Malnutrition, which is reflected by a low ALB level, could weaken defense mechanisms such as cellular and humoral immunity and phagocytic function, resulting in an increased possibility of infection and poor response to infection and anticancer treatment." (PMID 31662753, 2019). "Low serum albumin, together with lower haemoglobin levels, may be markers of malnutrition and/or chronic disease." (PMID 30606164, 2019). "Increasing albumin by appropriate nutrition is relevant in patients with malnutrition." (PMID 30637771, 2019). "Other studies have defined severe nutritional deficiency as per the European Society for Clinical Nutrition and Metabolism (ESPEN) guidelines: Weight loss > 10–15% in past 6 months, BMI < 18.5 kg/m2, SGA = C, NRS > 5, or albumin < 30 g/L." (PMID 31100877, 2019). "Noticeably, based on these two parameters alone, annual malnutrition reportage for Malaysian HD patients with 10-year trends from 2006 to 2015 have shown an increasing trend from 46 to 62% with serum albumin < 4.0 g/L, in contrast to a decreasing trend of BMI < 25 kg/m2 from 71 to 61%." (PMID 30514284, 2018).